YAP1 (Yes1 associated transcriptional regulator)
Diseases named in the same sentence as YAP1 in open-access papers (continued):
Sharing a sentence is not in itself a finding about the gene and the disease.
non-small cell lung carcinoma (45 papers, 2013 to 2025). A group of at least three distinct histological types of lung cancer, including non-small cell squamous cell carcinoma, adenocarcinoma, and large cell carcinoma. "cGAS-STING signaling pathway was also associated with the suppression of YAP1 in endothelial cells and non-small cell lung cancer." (PMID 37406004, 2023). "KRAS-mutated human non-small cell lung cancers are associated with increased nuclear YAP1, and downregulation of YAP1 has been shown to synergize with the chemotherapeutic agent, cisplatin." (PMID 30956771, 2019). "miR-25, which is overexpressed in non-small cell lung cancer and suppresses apoptosis, increases YAP1 levels by targeting LATS2." (PMID 33582842, 2021). "In non-small cell lung cancers, YAP1 transcriptionally induces SOX2 through a physical interaction with OCT4." (PMID 34199594, 2021). "A previous study showed that Yes-associated protein 1 (YAP1) contributed to the invasion and migration of non-small cell lung cancer by promoting Slug transcription via the transcription co-factor TEAD." (PMID 35155451, 2021). "Yes-associated protein 1 (YAP1) was identified as an oncogene in several cancers, including HCC, gastric adenocarcinoma, and non-small cell lung cancer." (PMID 32656089, 2020). "YAP1 induces the EMT in non-small cell lung cancer by regulating the transcription of Slug via interacting with TEAD42." (PMID 32728069, 2020). "LINC02159 promotes non-small cell lung cancer progression via ALYREF/YAP1 signaling." (PMID 40091620, 2025). "Another study revealed that blocking circ_0014130 could weaken the drug resistance of DTX-resistant non-small cell lung cancer via regulating miR-545-3p-YAP1 axis." (PMID 35659274, 2022). "Furthermore, miR-424-3p has been also proved to prevent proliferation, migration, and invasion of non-small-cell lung cancer cells as well as sensitize them to cisplatin and paclitaxel by inhibiting YAP1 protein." (PMID 30585294, 2019). "Yes-associated protein 1 (YAP1) contributes to the development of multiple tumors, but the mechanism underlying YAP1 deregulation in non-small cell lung cancer (NSCLC) remains unclear." (PMID 29700328, 2018). "Beyond YAP1-amplified malignancies, the concurrent inhibition of YAP-TEAD and MEK-RAF pathways demonstrated synthetic lethality in tumors harboring BRAF or RAS mutations, suggesting the promise of this strategy across a wide range of cancers, particularly melanoma and non-small cell lung cancer." (PMID 38067201, 2023). "And other studies have shown that YAP1 and cGAS-STING are positively correlated in non-small cell lung cancer." (PMID 40918140, 2025). "GMEB1 can promote the malignant proliferation and metastasis of HCC by promoting the transcription of the YAP1 promoter region; GMEB1 can also interact with USP40 to stabilize CFLARL in non-small cell lung cancer and inhibit cell apoptosis." (PMID 40625743, 2025). "In non-small cell lung cancer, hypoxia-inducible factor (HIF)-1α inhibits ferroptosis by activating the Hippo–YAP signaling pathway, and YAP1 upregulates GPX4 expression." (PMID 37773303, 2024). "In the present study, we found that the YAP1 inhibitor CA3 alone inhibits the proliferation, and migration of non-small cell lung cancer cells." (PMID 37215986, 2023). "Also, YAP1 regulates anaplastic lymphoma kinase (ALK) by inhibiting the anti-apoptotic factors MCL1 apoptosis regulator and Bcl-xL (B cell leukemia/lymphoma), which has clinical significance for molecular targeted therapy in non-small cell lung cancer with ALK-positive mutations." (PMID 34539895, 2021). "In addition, several studies have reported a negative impact of YAP1 activation on the survival of patients with gastric, colorectal, ovarian, bladder, and non-small cell lung cancer." (PMID 33718163, 2021).
non-small cell lung carcinoma (continued). "Unlike in non-small cell lung cancer (NSCLC) cases, where YAP1 is strongly expressed and contributes to oncogenic processes, YAP1 in SCLC appears to correlate with limited-stage disease, an inflamed tumor microenvironment, and improved prognosis." (PMID 40333678, 2025). "Notably, YAP1 is absent or expressed at low levels in SCLC cells, compared with non-small cell lung cancer (NSCLC) cells where it is strongly expressed [21, 22••]." (PMID 37870696, 2023).
cervical carcinoma (34 papers, 2014 to 2026). A carcinoma arising from either the exocervical squamous epithelium or the endocervical glandular epithelium. "HrHPV synergized with hyperactivated yes-associated protein 1 (YAP1) (from HIPPO/YAP1 pathway) to promote the initiation and progression of cervical cancer." (PMID 37372319, 2023). "For example, analysis of the TCGA database of patient tumors demonstrates that a subset of roughly ten percent of patients with cervical cancer shows focal amplification of YAP1, which in turn is associated with an increase in YAP1 transcriptional activity." (PMID 34685695, 2021). "As an example, up-regulation of miR-195-5p targets Yes-associated protein 1 (YAP1) to exert a tumor-suppressive role in cervical cancer." (PMID 34790697, 2021). "Apart from STK11, PIK3CA mutations and YAP1 amplification are prevalent cervical cancer drivers." (PMID 41742943, 2026). "Although YAP1 could be a possible predictive biomarker in cervical cancer, the particular pathways linked withYAP1-induced cervical cancer are currently being explored." (PMID 37886144, 2023). "We mined TCGA cervical cancer datasets and found that besides YAP1 amplification, the upstream genes of the Hippo pathway, including MST1, LATS1/2, and FAT1/2/3/4, which negatively regulate YAP1 activity, were frequently deleted and/or mutated in cervical cancer patient samples." (PMID 30840887, 2019). "This study investigates the interplay between ΔNp63, miR-141-3p, and YAP1 in the progression of cervical cancer." (PMID 40603978, 2025). "The Yes-associated protein (YAP1), a key activator of the Hippo signalingsystem, interacts with the HPV E6 oncoprotein to initiate and enhance cervical cancer progression." (PMID 37886144, 2023). "By regulating the expression of Yes1-associated transcriptional regulator (YAP1), miR-195-5p inhibits the malignant progression of cervical cancer." (PMID 35600383, 2022). "Other tumor indications with Hippo-YAP1 pathway alterations have also been reported, including tumors with YAP1 amplifications such as cervical cancer or tumors with NF2 deletions such as renal cell carcinoma and schwannomas meningiomas." (PMID 35689194, 2022). "In cervical cancer, hsa_circ_0023404 has been reported to play an oncogenic role by sponging miR-136 and subsequently modulating YAP1 expression." (PMID 35673576, 2022). "The YAP1-TEAD activity score was much lower in other tumor indications, e.g., cervical cancer, where YAP1-TEAD activation was also strongly associated with HIPPO-YAP1 genomic alterations." (PMID 35689194, 2022). "It was reported to hold a miRNA sponging mechanism by binding to miR-136 and subsequently altering YAP1 expression and its activity in cervical cancer." (PMID 35673576, 2022). "Our recent study demonstrated that overexpression of YAP1 in cervical cancer cells can overcome the contact inhibition-induced cell growth inhibition, promote cell cycle progression, and significantly stimulate cervical cancer cell growth in vitro and in vivo." (PMID 30840887, 2019). "Cervical epithelial cell-specific HPV16 E6/E7 and YAP1 double-knockin mouse model demonstrated that high-risk HPV synergized with hyperactivated YAP1 to promote the initiation and progression of cervical cancer." (PMID 30840887, 2019). "Cross-cancer genomic analyses based on TCGA datasets showed that the most frequent genomic alteration of the Hippo/YAP1 pathway occurs in the cervical carcinoma." (PMID 30840887, 2019). "In cervical cancer, YAP1 was amplified in the EMT cluster samples from TCGA data highlighting the potential role of this gene in EMT-related tumor progression." (PMID 30760827, 2019). "In conclusion, the in vitro and in vivo results from the present study show that YAP1, the major effector of the Hippo pathway, plays a central role in the development of cervical cancer." (PMID 30840887, 2019).
cervical carcinoma (continued). "Hyperactivation of YAP1 is sufficient to induce malignant transformation of cervical epithelial cells and development of invasive cervical cancer in mouse models." (PMID 30840887, 2019). "We found that hyperactivation of YAP1 in mouse cervical epithelium was sufficient to induce invasive cervical cancer." (PMID 30840887, 2019). "The major effector of the Hippo signalling pathway, the Yes-associated protein (YAP1), interacts with the HPV E6 oncoprotein to initiate and promote the progression of cervical cancer." (PMID 31319555, 2019). "In summary, these studies suggest that the Hippo/YAP1 pathway significantly contributes to cervical carcinogenesis partly due to HPV-induced activation of YAP1 that acts on both the initiation and progression of cervical cancer." (PMID 32038526, 2019). "Activation of YAP1 in cervical cancer cells significantly stimulated the expression of EGFR and its ligands TGFα and AREG." (PMID 30840887, 2019). "Although hyperactivation of YAP1 is sufficient to induce development of cervical cancer, it generally took 6–8 months to observe invasive cancer in the cervical epithelium under constitutive induction of YAP1 expression with low concentration of Dox." (PMID 30840887, 2019). "Cervical cancer tissues from advanced-stage patients had higher expression levels and more nuclear accumulation of YAP1 protein compared with those from early-stage patients (n = 68), indicating that the activity of YAP1 was elevated with cancer progression." (PMID 30840887, 2019). "Among the potential targeting genes, SOST, MTA1, TFRC, and YAP1 are involved in some important signaling pathways modulating cervical cancer cell invasion, migration, and drug sensitivity." (PMID 30344797, 2018). "These evidences, together with our data directly addressing YAP1 copy amplification, support that YAP1 is the target of the amplification at 11q22 locus in cervical carcinoma." (PMID 24810989, 2014). "YAP1 protein expression was assayed by immunohistochemistry in these cervical cancer samples, revealing that YAP1 protein level was higher in samples carrying YAP1 copy amplification compared to samples with normal YAP1 copy number (p=0.021)." (PMID 24810989, 2014). "YAP1 amplification was found in 4/25 (16%) cervical cancer samples, including high copy amplification in 3/4 and low copy amplification in 1/4." (PMID 24810989, 2014). "Patients with YAP1-amplified cervical cancer have poorer survival." (PMID 41646800, 2026). "Taken together, these results indicate that YAP1 acts as a key oncogene in promoting tumorigenic properties in both of studied cervical cancer cell lines, whereas the ∆Np63–miR-141-3p regulatory axis exhibits distinct, context-dependent roles in different cell lines." (PMID 40603978, 2025). "However, in cases such as cervical cancer, oncogenic mutations like Ras (G12D) or the loss of MST1/2 function can disrupt this regulatory control, allowing YAP1 to remain active." (PMID 40699764, 2025). "In cervical cancer, Hippo-YAP1 signaling could be a major driver in special designed mouse model which develops cervical cancer in situ immediately and this complicated progress may interfere with PI3K pathway activation." (PMID 38509907, 2024). "HPV in turn synergizes with YAP1 to promote the initiation and progression of cervical cancer." (PMID 30840887, 2019). "The results showed that YAP1, the oncogenic effector of the Hippo pathway, was frequently (11%) amplified, while LATS1/2, MST1, and FATs, which are upstream tumor suppressors of the Hippo pathway, were frequently deleted or mutated in cervical cancer patients." (PMID 30840887, 2019). "However, more functional studies on YAP1 amplification need to be conducted to elucidate its role in cervical cancer." (PMID 30760827, 2019).
cervical carcinoma (continued). "Although our animal model showed that hyperactivation of YAP1 is sufficient to induce the development of CVSCC, the strong epidemiological association between HPV infection and cervical cancer implies that HPV oncoproteins are involved in cervical tumorigenesis." (PMID 30840887, 2019). "The specific mechanisms associated withYAP1-induced cervical cancer are still being investigated, although YAP1 could be a potential prognostic biomarker in cervical cancer." (PMID 31319555, 2019). "Moreover, we found that the EGFR pathway was involved in YAP1-induced cervical cancer cell proliferation and migration." (PMID 30840887, 2019). "These in vivo data strongly support our hypothesis that HPV synergizes with hyperactivated YAP1 to drive initiation and progression of cervical cancer." (PMID 30840887, 2019). "Besides, YAP1 silencing also increases the sensitivity of cervical cancer cells to cisplatin treatment." (PMID 30344797, 2018). "HNSCC is the second most common YAP1-amplified cancer type (8.6%) after cervical cancer (12.6%), suggesting that YAP1 activation might be a critical genetic event for development of HNSCC." (PMID 29340043, 2017). "In particular, we detected YAP1 copy amplification in 4/25 (16%) of cervical cancer samples." (PMID 24810989, 2014). "Whether YAP1 copy amplification event represents a marker of cervical cancer progression and prognosis remains an intriguing but unexplored issue." (PMID 24810989, 2014). "In summary, our data highlights the different functions of ΔNp63-miR-141-3p-YAP1 axis in regulating proliferation, migration and invasion as well as EMT of different cervical cancer cells." (PMID 40603978, 2025). "We previously found that CDH6, YAP1, and OCT4 transcripts were highly expressed in the HeLa (cervical) cancer cell line." (PMID 35356283, 2022). "Norepinephrine induced the β-adrenergic/PKA activation of YAP-1, regulating the Hippo-YAP1 pathway resulting in anoikis resistance and tumour progression in cervical cancer cells." (PMID 33418900, 2021). "We found that YAP1, the major effector of the Hippo signaling pathway, interacted with HPV16 E6 oncoprotein to drive the initiation and progression of cervical cancer." (PMID 30840887, 2019). "Moreover, YAP1, CDH6 and OCT4 were significantly up-regulated in cervical cancer (p = 0.038, 8.98E-7 and 0.002, respectively)." (PMID 35356283, 2022). "In addition, circUBAP2 modulates cancer cell malignancy through the miR-641/YAP1 axis and miR-361-3p/SOX4 axis in osteosarcoma and cervical cancer, respectively." (PMID 33707417, 2021). "This trend is similar to that observed in other tumor types such as lung squamous carcinoma, skin melanoma, and cervical cancer, whereas YAP1 activation is absent in most sarcomas and lymphoid tumors, which, coincidentally, display low alteration rates in FAT genes (<5%)." (PMID 29985391, 2018). "The observation that hyperactivation of YAP1 induced expression of the putative HPV receptors and suppression of innate immune system in cervical epithelial cells indicates that HPV and YAP1 might function in a synergic manner to drive the development of cervical cancer." (PMID 30840887, 2019). "Considering that ΔNp63 and YAP1 are involved in the EMT process in CC and based on their negative correlation in two major histological cervical cancer cell lines, we aimed to investigate the interplay between ΔNp63 and YAP1 in the SCC CaSki and ADC HeLa cell lines." (PMID 40603978, 2025).
osteosarcoma (34 papers, 2013 to 2025). A usually aggressive malignant bone-forming mesenchymal neoplasm, predominantly affecting adolescents and young adults. "The inhibitory effect on osteosarcoma cell proliferation caused by FAT10 knockout can be reversed by YAP1 overexpression." (PMID 39062505, 2024). "In osteosarcomas, an abnormal degree of H19 expression has been detected, which can be promoted by amplified Hedgehog (Hh) signaling and upregulated yes-associated protein 1 (Yap1)." (PMID 39015175, 2024). "Yes-associated protein 1 (Yap1) is an oncogene that is highly expressed in human osteosarcoma tissues." (PMID 29899399, 2018). "However, Hh signaling is reactivated and upregulated in various cancers, including osteosarcoma, resulting in high levels of yes-associated protein 1 (Yap1) expression." (PMID 27685633, 2016). "For mechanisms, Prkci positively activates the Akt/mTOR signaling pathway in osteosarcoma; Prkci regulates the activity of the oncogenic transcription factor YAP1 by modulating binding of YAP1 to AMOT130 in ovarian cancer." (PMID 41188443, 2025). "Our results demonstrated that the HDACis sensitize osteosarcoma cells to VP16 by downregulating the Hippo/YAP1 signaling pathway." (PMID 41009501, 2025). "Altogether, our findings reveal that the Hippo/YAP1 signaling pathway is integral to the mechanism by which HDACis specifically potentiate the chemosensitivity of osteosarcoma cells to VP16." (PMID 41009501, 2025). "Aberrant Hh signaling induces the expression of Yap1 and H19 during the development of osteoblastic osteosarcoma." (PMID 40624028, 2025). "As another core ferroptosis-related lncRNA noted in this study, APTR has been shown to reduce miR-132-3p and enhance YAP1 expression, which in turn promotes osteosarcoma progression." (PMID 36923797, 2023). "This research aimed to elucidate the roles of USP10 and YAP1 in osteosarcoma EMT as well as distant metastasis." (PMID 37184153, 2023). "Based on these results, we can conclude that USP 10 changes the degradation and ubiquitin of YAP1 in osteosarcoma cells, thus stabilizing the expression of YAP1." (PMID 37184153, 2023). "The overexpression of YAP1 and H19 is responsible for the pathogenesis of osteosarcoma, indicating a positive relationship between YAP1 and H19." (PMID 34401209, 2021). "In osteosarcoma cells, YAP1 can regulate the expression of SOX2 by binding to two distinct DNA binding sites upstream and downstream of the SOX2 gene." (PMID 34199594, 2021). "APTR/miR‐132‐3p/YAP1 is a possible functional axis participating in the pathogenesis of osteosarcoma." (PMID 34094972, 2021). "A circular RNA expressed from the second exon of the FAT Atypical Cadherin 1 gene (circFAT1) was demonstrated to sponge the YAP suppressive microRNA miR-375, thus upregulating YAP1 in osteosarcoma." (PMID 32326412, 2020). "The effects of circFAT1/miR-375/YAP1 was evaluated on human osteosarcoma cells growth, apoptosis, migration, invasion and tumorigenesis." (PMID 30514309, 2018). "Inhibition of the Hh pathway decreases Yap1 levels, and the knockdown of Yap-1 clearly suppresses osteosarcoma progression." (PMID 29899399, 2018). "Recently, some studies have reported high expression of YAP1 in osteosarcoma specimens with subsequently a higher expression of target genes related to the Hippo pathway." (PMID 27608849, 2016). "When YAP1 was knocked down by shRNA in MG-63 osteosarcoma cell line, proliferation and invasion were inhibited through inactivation of RUNX2 signaling." (PMID 27608849, 2016). "High expression of YAP1 by immunohistochemistry in a series of biopsies of osteosarcomas compared to normal bone was reported by one study." (PMID 27608849, 2016). "In addition, Western blot experiments demonstrated a marked reduction in YAP1 expression in the osteosarcoma cells after combination treatment." (PMID 41009501, 2025).